SLC25A32 (solute carrier family 25 member 32)
Diseases named in the same sentence as SLC25A32 in open-access papers (continued):
Sharing a sentence is not in itself a finding about the gene and the disease.
tumor (continued). "For clinical-level applications, it can be suggested that patients with high SLC25A32 expression may have a greater chance of tumour metastasis and other malignant manifestations." (PMID 39624160, 2024). "However, the regulation and specific mechanisms of SLC25A32 in tumour progression require further investigation." (PMID 39624160, 2024). "The proteomic data complement the transcriptome view that SLC25A32 has differential mRNA and protein expression in pan-cancer and healthy tissues and may be involved in tumour development." (PMID 39624160, 2024). "SLC25A32 is abnormally expressed at the transcriptional and protein levels in most cancer types, with aberrant DNA promoter methylation and significant gene amplification in most tumours." (PMID 39624160, 2024). "It is further suggested that CNA pattern of SLC25A32 may be used as an index to judge the malignant degree of tumour in clinical diagnosis and treatment." (PMID 39624160, 2024). "Based on biological behaviours and functions at the single-cell level, SLC25A32 may positively correlate with malignant biological behaviours, such as metastasis, tumour differentiation, angiogenesis, and EMT." (PMID 39624160, 2024). "We show that SLC25A32 is highly amplified in different tumor types and that gene amplification correlates with increased mRNA expression and reduced patients ́ survival, emphasizing its prominent clinical relevance and high potential as a novel target for cancer therapy." (PMID 32166001, 2020). "Inhibition of SLC25A32 in vitro reduces cell proliferation in a subset of tumor cells." (PMID 32166001, 2020). "In addition to the controversial substrate specificity of SLC25A32, the role of this transporter during tumor progression is entirely uncharacterized." (PMID 32166001, 2020). "Moreover, SLC25A32 promotes tumor progression through MYC-mediated pathways." (PMID 41465541, 2025). "We hypothesised that SLC25A32 might similarly affect tumour cell metastasis and EMT in TNBC cells." (PMID 39624160, 2024). "Thus, SLC25A32 might influence tumour progression by regulating immune cell infiltration and function." (PMID 39624160, 2024). "Our results indicate that the reduction of mitochondrial FAD concentrations by targeting SLC25A32 has potential clinical applications as a single agent or in combination with approved cancer drugs that lead to increased oxidative stress and reduced tumor growth." (PMID 32166001, 2020). "Our findings suggest that the correlation between SLC25A32 methylation, CNV levels, and immune-related markers in some cancers provides new ideas for tumour immunotherapy response regulation." (PMID 39624160, 2024). "Our data support the role of SLC25A32 as a mitochondrial regulator of FAD levels and show that SLC25A32 knock-down in sensitive tumor cells results in defect at the FAD-dependent complex II enzyme, increased succinate levels and reduced OCR." (PMID 32166001, 2020). "However, its specific mechanism of action in tumour development is poorly understood owing to the lack of multiomics integrated analysis of SLC25A32 in pan-cancer." (PMID 39624160, 2024). "Interestingly, our data indicate that inhibition of SLC25A32 does not reduce the activity of the mitochondrial (M+1 dTTP) folate cycle and does not induce reversal of the cytosolic flux (M+2 dTTP) in neither sensitive nor resistant tumor cells." (PMID 32166001, 2020). "Furthermore, in contrast to published reports showing cancer cell dependency on mitochondrial folate enzymes only in the absence of extracellular serine, the knock-down of SLC25A32 in nutrient-replete conditions strongly inhibited proliferation of sensitive tumor cell lines in vitro." (PMID 32166001, 2020).
cancer (4 papers, 2020 to 2024). A tumor composed of atypical neoplastic, often pleomorphic cells that invade other tissues. "Both results indicate that SLC25A32 is significantly associated with prognosis in most cancer types and is a risk factor for cancer prognosis." (PMID 39624160, 2024). "The correlation suggests that promoter methylation may cause the altered SLC25A32 expression in some cancers." (PMID 39624160, 2024). "We then analysed the genetic and epigenetic mutations of SLC25A32 in pan-cancer." (PMID 39624160, 2024). "Notably, we summarised the association between SLC25A32 expression and related drug sensitivity in various cancer types based on the anti-cancer drug susceptibility database Genomics of Drug Sensitivity in Cancer (GDSC)." (PMID 39624160, 2024). "Therefore, SLC25A32 expression is closely associated with immune cell infiltration in various cancer types." (PMID 39624160, 2024). "SLC25A32 is widely differentially expressed in pan-cancer with prognostic significance and is correlated with immune infiltration." (PMID 39624160, 2024). "DCAF13 was strongly correlated with SLC25A32 in most cancers (R = 0.75), followed by FAM91A1 (R = 0.69) and TAF2 (R = 0.68)." (PMID 39624160, 2024). "We then utilised the relationship between SLC25A32 expression and TMB and MSI in most cancer types to investigate the relationship between SLC25A32 expression and immunotherapy." (PMID 39624160, 2024). "The GEPIA2.0 database revealed the differential expression of SLC25A32 in different pathological stages of various cancer types." (PMID 39624160, 2024). "In most cancers, SLC25A32 CNV types are mainly gene amplifications, and CNV alterations exhibit some correlation with their expression level." (PMID 39624160, 2024). "Overall, this study integrated expression, genetics, prognosis, immunity, and functional perspectives of SLC25A32, a novel pan-cancer prognosis gene, and immunotherapy-related biomarkers." (PMID 39624160, 2024). "This indicated that the Th1/Th2 ratio was significantly negatively correlated with SLC25A32 expression in almost all cancer types." (PMID 39624160, 2024). "For example, SLC25A32 had higher mRNA and protein levels in most cancers, indicating a worse prognosis, but in a few specific cancers, SLC25A32 expression was actually lower than that in normal tissues." (PMID 39624160, 2024). "Our findings revealed that SLC25A32 expression was positively correlated with TMB in some cancers, including DLBC, KICH, LUAD, and STAD." (PMID 39624160, 2024). "TCGA pan-cancer data from the cBioPortal platform was used to study the genetic alterations of SLC25A32, and the gene copy number of SLC25A32 was analysed in pan-cancer." (PMID 39624160, 2024). "Due to the importance of FAD, folate, and one-carbon metabolism, SLC25A32 is expected to play a central role in cancer pathogenesis." (PMID 39795950, 2024). "In summary, SLC25A32 is upregulated in various types of cancer and is involved in promoting cell metabolism by increasing the availability of FAD in the mitochondrial matrix while decreasing ROS production." (PMID 39795950, 2024). "The study validates the role of SLC25A32 as a novel cancer target involved in the regulation of FAD-dependent mitochondrial metabolism." (PMID 32166001, 2020). "siRNA-mediated knock-down and CRISPR-mediated knock-out of SLC25A32 in cancer cells of different origins, resulted in the identification of cell lines sensitive and resistant to SLC25A32 inhibition." (PMID 32166001, 2020). "While both siRNAs strongly reduced SLC25A32 mRNA levels in all cancer cell lines analyzed, the effects exhibited on cell proliferation were different." (PMID 32166001, 2020). "While it is known that cancer cells require one-carbon and FAD-dependent mitochondrial metabolism to sustain cell proliferation, the role of SLC25A32 in cancer cell growth remains unexplored." (PMID 32166001, 2020).
cancer (continued). "Treatment of cells with the FAD precursor riboflavin and with GSH rescues cancer cell proliferation upon SLC25A32 down-regulation." (PMID 32166001, 2020). "Furthermore, the GSCA and cBioPortal databases were used to evaluate the inheritance impact and epigenetic alterations of SLC25A32 in pan-cancer." (PMID 39624160, 2024). "Notably, CD4 T cell infiltration determined using the XECLL algorithm revealed that Th1 cell infiltration was negatively correlated with SLC25A32 expression in almost all cancer types." (PMID 39624160, 2024). "Furthermore, the OS, progressive-free interval (PFI), and disease-specific survival (DSS) data of SLC25A32 in different cancer types were analysed using the UCSCXenaShiny database." (PMID 39624160, 2024). "Thus, we calculated the correlation between SLC25A32 expression and different immune cell infiltration in multiple cancer types." (PMID 39624160, 2024). "In addition, we explored the correlation of SLC25A32 with biological behaviours and functions in single-cell datasets of different cancers." (PMID 39624160, 2024). "In support of our work proposing SLC25A32 as novel cancer target regulating oxidative-stress metabolism, other studies have also shown the potential of ROS-inducing therapies as effective anti-cancer strategies." (PMID 32166001, 2020). "Molecular targeting of SLC25A32 using a single agent or in combination with ROS-inducing therapies could be an effective clinical strategy to successfully treat cancer patients." (PMID 32166001, 2020). "Therefore, we analysed the gene mutations of SLC25A32 and CNV in pan-cancer." (PMID 39624160, 2024). "Therefore, we investigated the promoter methylation level of SLC25A32 in pan-cancer." (PMID 39624160, 2024). "To understand the mechanisms associated with the selected four SLCs, we performed GSEA to identify pathways enriched in cancers with high expression of SLC16A3, SLC53A1, SLC25A32, and SLC2A3." (PMID 39335197, 2024). "SLC25A32 inhibition leads to respiratory chain dysfunction of FAD-dependent complex II enzymes, reactive oxygen species (ROS) induction, and reduced glutathione (GSH) depletion, which impairs cancer cell proliferation." (PMID 39624160, 2024). "Overall, our data suggest that SLC25A32 is an important mitochondrial regulator in cancer cells to maintain mitochondrial FAD levels and that its inhibition represents a potential new strategy to treat cancer by inducing ROS-mediated cancer cell death." (PMID 32166001, 2020). "Despite the lack of published reports directly linking SLC25A32 to cancer, the role of one-carbon and folate metabolism in cancer cell survival is well established." (PMID 32166001, 2020). "Instead, SLC25A32 inhibition results in a respiratory chain dysfunction at the FAD-dependent complex II enzyme, induction of Reactive Oxygen Species (ROS) and depletion of reduced glutathione (GSH), which impairs cancer cell proliferation." (PMID 32166001, 2020). "Our work highlights the importance of SLC25A32 as a novel regulator of cancer cell proliferation and mitochondrial FAD metabolism, since until now its function remains unknown in the field of cancer research." (PMID 32166001, 2020). "Our findings therefore suggest that SLC25A32 down-regulation does not alter the mitochondrial/cytosolic folate cycle and that cancer cell dependency on SLC25A32 expression might be driven by other pathways than serine-derived mitochondrial one-carbon metabolism." (PMID 32166001, 2020).
metabolic disease (1 paper, 2024). A congenital disorder (due to inherited enzyme abnormality) or acquired (due to failure of a metabolically important organ) disorder resulting from an abnormal metabolic process. "Mutations in SLC25A32 in humans cause late-onset exercise intolerance, which is associated with various neurological and metabolic diseases." (PMID 39624160, 2024). "Studies on SLC25A32 have focused on neurological and metabolic diseases, where its mutations in humans lead to riboflavin-responsive motor intolerance." (PMID 39624160, 2024).
SLC25A32 also shares sentences with these, for which no sentence is quoted: ovarian serous cystadenocarcinoma (2 papers); Ataxia (1); diffuse large B-cell lymphoma (1); infection (1); lung adenocarcinoma (1); lung carcinoma (1); lymphoid neoplasm (1); metabolic syndrome (1); myelomeningocele (1); nasopharyngeal carcinoma (1); neuroblastoma (1); neurological diseases (1); pancreatic adenocarcinoma (1); sarcoma (1); silicosis (1); triple-negative breast carcinoma (1); uterine carcinosarcoma (1).